EGFR (epidermal growth factor receptor)
Diseases named in the same sentence as EGFR in open-access papers (continued):
Sharing a sentence is not in itself a finding about the gene and the disease.
tumor (continued). "The biomarker results indicate that PFS and OS benefit in patients with high EGFR gene copy number in their tumours appears to be derived from overlapping EGFR mutation positivity." (PMID 21654681, 2011). "High EGFR expression was detected in 28% of tumours, associated with grade and stage (P=0.05; P=0.04)." (PMID 21364580, 2011). "This overexpression has been linked to disease recurrence in which EGFR-dependent signaling pathways are activated, leading to tumor cell proliferation and anti-apoptosis." (PMID 21917153, 2011). "Results from this and previous studies therefore suggest that EBUS-TBNA can provide sufficient tumour material for EGFR and KRAS mutation analysis in routine clinical practice thus avoiding the need for more invasive surgical sampling in these patients." (PMID 21949883, 2011). "Together with somatic mutations, increased EGFR gene copy number in tumor emerged as another important predictor for TKI sensitivity." (PMID 24212786, 2011). "The sequential accumulation of de novo mutations in tumor cells makes it difficult to predict sensitivity to EGFR-TKI." (PMID 22108465, 2011). "Generally, our result was consistent with that of OPTIMAL and IPASS research, both using tumor tissue for EGFR mutation analysis." (PMID 22142557, 2011). "A recent meta-analysis demonstrated 3% rate of objective tumor response to EGFR TKIs in patients with KRAS mutations, as compared to 26% in those with wild-type KRAS." (PMID 21444946, 2011). "We showed that tissue from the primary tumour can reliably be used for KRAS mutation testing in order to select patients for anti-EGFR therapy." (PMID 21364579, 2011). "The epidermal growth factor receptor (EGFR) signaling pathway is importantly implicated in tumor cell growth, local invasion, angiogenesis, metastasis, protein translation and cell metabolism." (PMID 21444946, 2011). "EGFR expression (or overexpression), typically determined by immunohistochemistry, has been found to be associated with tumor progression and poor survival in various malignancies, such as carcinomas of the head and neck." (PMID 21403829, 2011). "In summary, we found that 36% of the patients in this series had EGFR-overexpressing tumours and that this feature was significantly associated with biochemical relapse." (PMID 21266046, 2011). "Of 100 patients who underwent surgical resection of their tumours, 13 presented point mutations (13%) in the TK domain of EGFR." (PMID 21266046, 2011). "In three trials (SATURN, BR.21 and ISEL), patients with tumours showing positive EGFR immunostaining had a significantly reduced risk of death or progression with TKI treatment vs placebo with hazard ratios (HRs) of 0.68–0.77 in favour of EGFR TKI therapy." (PMID 21654681, 2011). "Tumor biomarker analysis of EGFR mutation status was available for 437 patients: those with EGFR mutation had median PFS of 44.6 weeks on erlotinib compared to 13 weeks with placebo (HR = 0.1), a remarkable benefit for this subgroup of patients." (PMID 21444946, 2011). "Another 29 genes were found to be differently modulated in mutated tumours according to their EGFR expression level (high vs low)." (PMID 21266046, 2011). "Low ER expression, high EGFR expression, activation of poor prognosis profile signatures, large tumour size and high histological grade all associated significantly with high cPLA2α mRNA expression." (PMID 21119660, 2011). "Even when an EGFR-mutated tumor is initially controlled with EGFR inhibition, resistance emerges typically after a median of 9–12 months." (PMID 21785682, 2011). "On the other hand, the presence of CCND1 and EGFR numerical aberrations of the primary tumour was significantly associated with the presence of ECS in metastatic lymph nodes (P=0.011 and 0.004, respectively)." (PMID 21304522, 2011).
tumor (continued). "ERBB2 and EGFR gene amplification were significantly associated with the depth of tumor invasion (P < 0.05) and lymph node metastasis (P < 0.05), but not with sex, age, or histological type (P > 0.05)." (PMID 21689422, 2011). "Two of the main problems associated with administering EGFR-targeted toxins in tumor therapy are severe systemic side effects and low transfer of the toxins into the cytosol after binding to the tumor cell surface." (PMID 22069735, 2011). "In the present study, we investigate KRAS and EGFR mutation status using PCR-based sequencing analyses in 80 primary tumor samples and their corresponding local lymph node metastases from Chinese patients with NSCLC." (PMID 21414214, 2011). "The mutation-specific antibodies (L858R point mutation and E746-A750 deletion in exon 19), total EGFR antibody and pan-cytokeratin were used to stain the 143 tumor sections." (PMID 21858063, 2011). "The EGFR is commonly overexpressed or mutated in many cancer types and its presence promotes tumor progression and survival." (PMID 24212795, 2011). "Since activation of the EGFR pathway is associated with increased tumor aggressiveness and decreased survival in PDAC, we sought to determine the effect of EGF on motility." (PMID 22053213, 2011). "In cancer cells, EGFR is frequently over-expressed and is associated with tumor proliferation, progression and drug resistance." (PMID 21388543, 2011). "First, although we and others have demonstrated that body fluid is feasible, analysis for EGFR mutations with DNA extracted from tumor tissue remains the gold standard." (PMID 22142557, 2011). "Multiple mechanisms allow for EGFR activation and persistent tumor cell proliferation, including activating mutations, receptor amplification, and ligand up-regulation." (PMID 21255411, 2011). "After this seminal discovery, evidence accumulated in recent years has supported the idea that patients harbouring these mutations in their tumours show response to EGFR tyrosine kinase inhibitors." (PMID 21575252, 2011). "pyrosequencing is then a highly accurate method for detecting ΔLRE and L858R EGFR mutations in patients with NSCLC when the samples contain at least 20% of tumor cells." (PMID 21575212, 2011). "AKT, which affects tumor cell motility and invasiveness, is also part of the EGFR-associated signaling network." (PMID 21939503, 2011). "Epidermal growth factor receptor (EGFR) is overexpressed in a variety of human tumours including GBM, where it has been linked to radiation resistance and poor prognosis." (PMID 21934682, 2011). "Because EGFR-overexpression is a hallmark of advanced epithelium-derived tumors, anti-EGFR antibodies bind preferentially to tumor cells." (PMID 24212794, 2011). "Patients characterized by elevated EGFR and elevated Aurora-A protein expression in tumor tissue represent a risk group with poor disease-free and overall survival (EGFRlow Aurora-Alow versus EGFRhigh Aurora-Ahigh, p = 0.024)." (PMID 21865609, 2011). "The results of two phase III Japanese trials comparing gefitinib and chemotherapy as first-line treatment in NSCLC patients exclusively with tumours harbouring EGFR mutations confirmed improved outcomes with EGFR TKIs." (PMID 21654681, 2011). "EGFR protein overexpression (EGFRhigh) was found in 36% of the tumour samples, and mutations were found in 13% of samples." (PMID 21266046, 2011). "It is possible that a tumor with wild-type EGFR before front-line chemotherapy can become an alternative tumor, harboring the EGFR-activating mutation." (PMID 22108465, 2011). "One sample that gave uninformative sequence also failed EGFR mutation analysis due to paucity of tumour material." (PMID 21949883, 2011). "On the contrary, second but most interesting and important finding of this study was that ECS in the metastatic lymph node is significantly associated with EGFR numerical aberrations at the primary tumours." (PMID 21304522, 2011).
tumor (continued). "An important issue is when to use EGFR TKI in patients who have EGFR mutations in their tumours – should these agents be administered as first-line, maintenance or as second/third-line treatment?" (PMID 21654681, 2011). "The response to EGFR tyrosine kinase inhibitor (EGFR-TKI) has been shown to be closely related to the somatic activating mutation of the EGFR gene in tumor cells." (PMID 22108465, 2011). "Of note, tumour samples from the patient who experienced a partial response demonstrated a mutation in the EGFR kinase domain." (PMID 21364581, 2011). "By using this method, the sensitivity and specificity of plasma EGFR mutation analysis reached 92% and 100% respectively, as compared with the sequencing results of tumor samples." (PMID 22142557, 2011). "Although present in normal cells, EGFR overexpression in tumor cells has been associated with a poor prognosis and decreased survival and EGFR activation is also involved in resistance to chemotherapy and radiation treatment." (PMID 22135505, 2011). "In HCC, overexpression of EGFR has been associated with late-stage disease, increased cell proliferation, and the degree of tumor differentiation." (PMID 21829460, 2011). "An additional explanation for the suboptimal response rates to anti-EGFR antibodies in patients with KRAS wild-type tumours is discordance of KRAS mutation status between primary colorectal tumours and corresponding metastases." (PMID 21364579, 2011). "Metastatic CRC patients with tumours harbouring a KRAS mutation are resistant to treatment with anti-EGFR antibodies, showing lower response rates, decreased progression-free survival, and overall survival compared with patients with KRAS wild-type tumours." (PMID 21364579, 2011). "EGFR over expression or mutations leads to abnormal EGFR signaling which is linked to the development of many tumours." (PMID 22193779, 2011). "Mutation screening of 24 tumor samples by dideoxy sequencing revealed short in-frame nucleotide deletions in EGFR exon 19 in eight samples and only one sample (case 03) harbored the L858R point mutation in exon 21 of EGFR." (PMID 21573178, 2011). "Mutational analysis revealed that 13 out of 100 patients had tumours carrying mutations in the EGFR TK domain." (PMID 21266046, 2011). "EGFR mutations were analysed in 10 of 27 patients by direct sequencing of paraffin-embedded tumour samples extracted before initiation of gefitinib therapy." (PMID 21915126, 2011). "In 12 cases (40%), EGFR promoter methylation resulted biallelic, whereas in the remaining 18 tumours (60%) only one allele resulted methylated." (PMID 21559018, 2011). "Taken into account that YB-1 expression is linked to multi drug resistance in various tumour entities so far as well as against EGFR-tailored drugs YB-1 expression was also found to be also involved in cancer stem cell biology and trastuzumab resistance." (PMID 22095225, 2011). "Preclinical work suggests that the striking benefit of EGFR TKI therapies in mutation-positive tumours is related to massive apoptosis." (PMID 22095222, 2011). "Mutations at this position in the EGFR gene have also been discovered in tumours as somatic mutations." (PMID 21575252, 2011). "In placebo-controlled phase III studies of gefitinib and erlotinib, patients with EGFR-mutated tumours had significantly higher RR compared with patients with wild-type tumours." (PMID 21654681, 2011). "Much effort is thus being directed at understanding the mechanisms that underlie tumor resistance to anti-EGFR therapy." (PMID 21388543, 2011). "Amphiregulin and epiregulin are ligands of EGFR and high gene expression is thought to reflect greater dependence of tumor growth on the EGF pathway and thus, greater susceptibility to EGFR inhibition." (PMID 24212785, 2011).
tumor (continued). "The high incidence of oncogenic KRAS activating mutations found in PDAC (90% of tumours) has been proposed as a contributing factor to the limited effects of EGFR targeting." (PMID 21792199, 2011). "Although phospho-EGFR was unrelated to clinicopathological variables, strong EGFR intensity was associated with higher tumour stage (P=0.03)." (PMID 19997103, 2010). "We also analyzed tumor EGFR DNA for the presence of activating mutations that predict for response to EGFR-TKIs." (PMID 20961434, 2010). "It is clear that much work is still needed to understand the relationship between circulating ligands in patient serum, tumor expression of ligands and receptors as well as EGFR mutation status." (PMID 21390244, 2010). "With respect to its predictive role, several retrospective analyses of tumour samples in CRC patients receiving anti-EGFR antibody treatment have shown that patients with mutated KRAS did not benefit from anti-EGFR therapy." (PMID 20959826, 2010). "While its activation stimulates tumor proliferation, overexpression of EGFR in various epithelial tumors is associated with a poor patient prognosis." (PMID 20509969, 2010). "For EGFR mutation analysis, tumor areas of interest were identified, microdissected, and collected cells lysed." (PMID 20961434, 2010). "We found that strong EGFR intensity was significantly associated with higher tumour stage (III vs II) as compared with weaker EGFR intensity." (PMID 19997103, 2010). "A clear example of this was the large randomized trial that demonstrated the presence of the EGFR gene mutation in a tumor as a strong predictor of a better outcome for EGFR inhibitor treatment." (PMID 24281115, 2010). "In a recent publication on EGFR expression in 236 cases of CC EGFR expression was a significant prognostic factor and also a risk factor for tumour recurrence in intrahepatic CC." (PMID 20565817, 2010). "The EGFR activating mutations and increased EGFR gene copy number identify the most sensitive population in these tumours." (PMID 20664595, 2010). "In a previous study, we developed a highly sensitive molecular method for detecting EGFR mutations in NSCLC samples containing as few as eight tumor cells." (PMID 21167064, 2010). "The aim of this study is to evaluate DHPLC as a rapid detection method for EGFR mutations in NSCLC tumor specimens." (PMID 20840812, 2010). "G3's effect on in vivo local tumor growth was associated with changes in EGFR signaling, and p-ERK expression levels were observed to be more than two-fold greater in primary tumors of G3 treated mice as compared with those of the vector control group." (PMID 21079779, 2010). "Lu and colleagues demonstrated that EGF treatment of human tumor cells that over express EGFR caused a dramatic alteration in cell-cell contacts and internalization of E-cadherin." (PMID 20540763, 2010). "Mycoplasma hyorhinis promoted tumor cell migration, invasion and metastasis in vitro and in vivo, which was possibly associated with the enhanced phosphorylation of EGFR and ERK1/2." (PMID 21062494, 2010). "Recent studies report a mutant allele specific imbalance of oncogenes in tumor cells harboring gene mutation; copy number gain of EGFR usually occurred in the cells with an EGFR mutation." (PMID 20637128, 2010). "K-Ras mutation status has recently been convincingly associated with response to the new generation EGFR antagonists cetuximab (Erbitux) and panitumumab (Vectibix), where response is preferentially observed in wt K-Ras tumours." (PMID 20147967, 2010).
tumor (continued). "Lately, it has become quite clear that the best predictor of a major clinical response is the presence of activating EGFR mutations in the tumor, mainly exon 19 deletions or L858R mutation." (PMID 21165163, 2010). "Regarding epidermal growth factor receptor (EGFR) gene mutations, tumor samples of 34 patients (31.5%) were analyzed and 21 were positive for mutations." (PMID 21114867, 2010). "EGFR mutations in exon 18-21 and K-ras mutations in exon 1 and 2 were detected in tumor samples from 101 Chinese patients with CRC by polymerase chain reaction-single strand conformational polymorphism." (PMID 20184776, 2010). "In BTC, a 13-15% tyrosine kinase domain mutation rate has been reported and it has been suggested that patients with tumor associated EGFR mutations be preferentially enrolled in clinical trials of EGFR-TKIs." (PMID 20961434, 2010). "Certain patient subsets are particularly responsive to these drugs such as patients whose tumor harbors activating EGFR mutations within the EGFR TKI domain." (PMID 21390244, 2010). "The percentage of PTEN labeled nuclei in tumor samples with activating EGFR or PI3K mutations was higher than in tissues with EGFR and PI3K wild type displaying 62%+31 (score 3+) vs 39%+26 (score 2+) respectively (p = 0.032)." (PMID 21087480, 2010). "Factors associated with tumor sensitivity to epidermal growth factor receptor (EGFR) inhibitors in the context of wild-type EGFR remain elusive." (PMID 20975924, 2010). "Some studies have reported an association between the overexpression of EGFR and poor tumor differentiation in OSCC." (PMID 20429940, 2010). "EGFR overexpression was significantly associated with poor tumor differentiation (P = .02) and a positive nodal stage (P = .032)." (PMID 19696947, 2009). "Tumor-like overgrowth was only observed in dEGFR-dRas85D;dPTEN−/− cells, illustrating that chronic EGFR-Ras activation and PTEN loss can cause cell-autonomous over-proliferation." (PMID 19214224, 2009). "Another secondary mutation (D761Y) in EGFR was identified in an NSCLC brain metastasis originating from a primary tumour that initially responded to gefitinib-based therapy." (PMID 19240716, 2009). "Recent phase II and III trials have shown that the presence of a K-ras mutation in tumours predicts response to EGFR-targeted therapy." (PMID 19401697, 2009). "SCCHN tumor expression of the truncated form of EGFR, EGFR variant III (vIII), which lacks the ligand binding domain, occurs in up to 40% of SCCHN tumors and confers resistance to EGFR-targeted monoclonal antibodies in SCCHN preclinical models." (PMID 19636423, 2009). "Evaluation of EGFR-targeted therapies in HNSCC-patients was based on the observation that EGFR is highly expressed in many tumours and that EGFR overexpression was associated with reduced survival in several studies." (PMID 19828033, 2009). "In view of this novel concept, an increased EGFR expression in PCa because of loss of androgen-dependent regulation would enhance tumour growth, invasion, and metastasis due to increased EGFR in tumour cells." (PMID 19888222, 2009). "All KRAS, BRAF, and EGFR mutations were mutually exclusive across different tumor types while some PIK3CA mutant cases also harbored one of the other three mutations." (PMID 19826477, 2009). "It is postulated that tumors harboring EGFR mutations demonstrate inflexible “tumor addiction” to the high EGFR transduction environment since they were born out of this condition." (PMID 20130810, 2009). "Several studies have demonstrated that EGFR is over-expressed in tumors and that it is associated with the appearance of tumor cells in lymph nodes in different human neoplasias." (PMID 19491505, 2009).